TNF (tumor necrosis factor)
Diseases named in the same sentence as TNF in open-access papers (continued):
Sharing a sentence is not in itself a finding about the gene and the disease.
tumor (continued). "Systemic toxicity and anti-tumour activity of TNF are both increased by local hyperthermia." (PMID 7779705, 1995). "Following normothermia, tumour cures were observed at TNF concentrations of 1000-1300 micrograms kg-1, while this was observed at doses of 50-300 micrograms kg-1 when combined with hyperthermia (TCD50 values of 1211 and 188 micrograms kg-1 respectively), resulting in a TER of 6.4." (PMID 7779705, 1995). "We conclude that TNF-alpha and IL-1 beta are released when an effector and tumour target cell are united by a specific tumour antibody and that these cytokines may be important in bringing about tumour cell lysis during the ADCC reaction." (PMID 7669568, 1995). "Antisense ICAM-1 oligonucleotide inhibited lysis by NK cells of TNF-alpha-treated tumour cells." (PMID 7908214, 1994). "After modification with an antimicrobial peptide, the expression level of TNF-α also increased due to the regulation of the inflammatory tumour microenvironment by antimicrobial peptides to further activate the body’s immune response and achieve the clearance of tumour cells." (PMID 41484054, 2026). "Importantly, activated dendritic cells producing TNF-α correlated with increased tumor-infiltrating T cell frequencies, heightened TNF-α production by CD8+ T cells, and a concurrent reduction in Tregs, further contributing to a less immunosuppressive tumor milieu." (PMID 41522339, 2026). "Therefore, we investigated whether Slc6a6 could also be expressed in the nucleus of PyMT tumor cells under TNF-α stimulated conditions." (PMID 41597281, 2026). "Besides directly affecting tumor cells, TNFα signaling significantly impacts the behavior of TAMs." (PMID 41041337, 2025). "However, MAIT cells often accumulate in tumors where they may produce TNF-α, IL-17, or IL-13-cytokines known to enhance tumor growth and suppress cytotoxic immunity." (PMID 41148807, 2025). "With TNFaip2 as a primary response gene of TNFα and highly expressed in immune cells, the decrease of TNFaip2 in CHRNA7KO BMDCs could be associated with a loss of responsiveness to inflammatory molecules in the tumor microenvironment of a CHRNA7KO host." (PMID 40653990, 2025). "Besides, serum TNF-α and IL-6 levels were reduced after Z526 treatment in C26 tumor-bearing mice." (PMID 39759112, 2025). "Likewise, circ‐ATP synthase 5H (circ‐ATP5H) exhibits significant oncogenic effects in HBV‐related HCC, promoting both HBV DNA replication and tumor cell proliferation by sponging miR‐138‐5p and regulating tumor necrosis factor α (TNF‐α)‐induced protein 3 (TNFAIP3)." (PMID 40060195, 2025). "In addition, elevated TNF-α and IL-6 levels in the serum of C26 tumor-bearing mice were observed, which could be down-regulated to near-normal levels by Z526." (PMID 39759112, 2025). "Additionally, TNF-α enhances the tumor microenvironment by recruiting immunosuppressive cells such as myeloid-derived suppressor cells (MDSCs) and Tregs, thereby facilitating tumor immune escape." (PMID 40430212, 2025). "Several miRNAs have been shown to directly target transcripts encoding TNF-α, TNF receptors, and associated signaling mediators, suggesting that miRNA dysregulation may significantly influence inflammatory signaling and tumor dynamics." (PMID 40565357, 2025). "The persistent presence of TNF-α in the TME may enhance tumor cell resistance to apoptosis." (PMID 40422233, 2025). "Notably, TNF-α operates at the intersection of inflammation and tumor biology." (PMID 40565357, 2025). "Furthermore, in DEN-induced HCC models, loss of the vitamin D-upregulated protein 1 (VDUP1) led to increased tumor growth, enhanced cell proliferation, elevated TNF-α levels, and NF-κB activation, reinforcing the role of vitamin D–mediated pathways in hepatocarcinogenesis." (PMID 41041128, 2025).
tumor (continued). "Interestingly, in preclinical models, TIM-3+/PD-1+ tumor-infiltrating lymphocytes (TILs) are characterized by significantly impaired proliferation and reduced cytokine production (IL-2, tumor necrosis factor [TNF], and IFN-γ) with a more severe exhausted phenotype than TIM-3−/PD-1+ TILs." (PMID 40508202, 2025). "Additionally, increased inflammatory factors such as TNF-α and IL-6 can alter the local immune microenvironment of the thyroid, inhibiting immune cells from recognizing and attacking tumor cells, making it easier for tumor cells to develop and progress." (PMID 40430234, 2025). "Additionally, TNF-α up-regulation observed with Carvacrol treatment may provide further tumor suppression." (PMID 41369848, 2025). "It is possible to speculate that HO induce basal release of TNF-α from MCs via an IL-33-independent mechanism, while, in tumor conditions, the IL-33 present in the co-culture can induce a greater release of TNF-α which may be responsible for the effects observed on TO." (PMID 40372523, 2025). "Collectively, these results demonstrate that OTUD4 suppresses TNF-induced NF-κB signaling by removing K63-linked Ub chains from the TAK1 signalosome, a function that depends on intrinsic catalytic activity and is abolished by the tumor-associated H148Y variant." (PMID 41062071, 2025). "Molecular insights from in silico analyses further indicated that PCNA inhibition may affect cell cycle regulatory mechanisms, while TNF-α suppression may influence TLR-associated signaling pathways, suggesting a possible modulatory role of skimmianine in tumor progression." (PMID 40430573, 2025). "MMW irradiation also induced tumor cells to secrete higher levels of immune-activating factors, such as tumor necrosis factor-α (TNF-α), interleukin-6 (IL-6), and interleukin-12 (IL-12), which could enhance the immune response of the body and thus clear the residual tumor more effectively." (PMID 41383334, 2025). "Considering the known antagonistic cross-talk between tumor necrosis factor-alpha (TNF) and TGFβ in cancer, the reduction of TGFβf in the tumor microenvironment caused by 5a-HSA might have contributed to the synergism observed between 5a-HSA and S-NGR-TNF in mice." (PMID 40055773, 2025). "Additionally, TNF-α can have anti-tumor effects in acute contexts, so timing and context matter." (PMID 41007766, 2025). "However, chronic TNF-α exposure within inflammatory environments can paradoxically promote carcinogenesis by sustaining NF-κB activation, enhancing angiogenesis, and inducing DNA damage, thereby facilitating malignant transformation and tumor progression." (PMID 41302997, 2025). "Furthermore, a comparison of individual perilymph levels from three VS patients with in vitro tumor-secreted levels showed that perilymph levels of TWEAK and TNF-α are proportional to the secretory capacity of the VS tissue, suggesting their origin from the VS tumor." (PMID 39923035, 2025). "In addition, CC-3 induced secretion of antitumor cytokines (IFN-γ, TNF, IL-2) and effector molecules (granzymes, perforin, and granulysin), which are known to promote tumor cell death, and also induced potent and long-lasting tumor cell lysis by the activated T cells." (PMID 40707958, 2025). "However, it is important to consider that neoadjuvant treatment is typically administered for larger tumor masses, which may also influence overall TNF-α concentrations." (PMID 41153842, 2025). "In addition, IFN-γ, TNF, interleukins, and other cytokines also modulates tumor biology." (PMID 40313931, 2025). "TNF-α may affect the recruitment and activation of immune cells within the tumor, resulting in a dynamic interaction between immune responses that promote and suppress tumor growth." (PMID 40933989, 2025).
tumor (continued). "Regarding previously published work attesting the central roles of IL-6 and TNFα in TGCTs as well as our own results implicating these cytokines in tumor–immune interactions, we wondered about their specific relevance for the effect of the cytokine milieu on the tumor cells themselves." (PMID 40649953, 2025). "Importantly, HYP-PDT modulated cytokine secretion, significantly decreasing IL-6 and IL-8 levels while increasing TNF-α, suggesting a shift toward a pro-inflammatory microenvironment that could enhance anti-tumor immune responses." (PMID 41226910, 2025). "The inflammatory process in GBM is driven by complex interactions between tumor cells and the tumor microenvironment, which involve changes in the concentration and activity of numerous cytokines and chemokines, including IL-6, IL-1β, and tumor necrosis factor α (TNF-α)." (PMID 40497976, 2025). "Notably, the treatment of TNF-α-activated MDA-MB-231 tumor cells with the proteasome inhibitor MG132, which blocks Nf-κB activity, significantly reduces cell aggregation, while anti-ICAM-1 monoclonal antibodies significantly decrease the number of hetero-aggregates attached to the endothelium." (PMID 40427136, 2025). "Moreover, HA@CD36i‐TR@siSCD1 had a potent immune‐enhancing effect, increasing the proportion of CD8+ T cells, decreasing the number of CD4+FoxP3+ Treg cells, promoting the release of the tumor killer factors TNF‐α and IFN‐γ, and transforming refractory PCa from “cold” tumors to “hot” tumors." (PMID 39736148, 2025). "Furthermore, we previously identified tumor-secreted factors such as tumor necrosis factor-alpha (TNF-α) and IL-6 as candidate ototoxic molecules that could be associated with hearing loss in VS patients." (PMID 39923035, 2025). "To determine whether recombinant human IFN-γ and TNF-α treatment of hA549 cells is capable of differentiating the hA549 tumor cells, we treated them with rhIFN-γ and rhTNF-α before we tested the NK cell-mediated cytotoxicity and chemo-drug induced killing of hA549 cells." (PMID 39851518, 2025). "Within the tumor microenvironment, cNK cells showed the lowest CD107a expression, indicating impaired degranulation, while ILC1-like cells produced substantial amounts of TNF-α, a pro-inflammatory cytokine that has been associated with tumor progression and poor prognosis in HCC." (PMID 41268557, 2025). "Single cell sequencing of murine organotypic tumor spheroids undergoing programmed cell death protein 1 (PD-1) blockade, identified a discrete subpopulation of immunotherapy persister cells vulnerable to tumor necrosis factor alpha (TNF-α)–induced cytotoxicity." (PMID 41050078, 2025). "However, when its expression becomes chronic, TNF-α may shift roles and support tumor development by contributing to tissue remodeling, angiogenesis, and facilitating tumor growth and metastasis." (PMID 40869161, 2025). "Thus, a skimmianine-induced reduction in TNF-α expression may be associated with altered inflammatory signaling in the TME, which could play a role in modulating tumor behavior." (PMID 40430573, 2025). "Furthermore, it was found through ELISA detection that in the co-culture system with the two tumor cells, the levels of IL-2, TNF-α and Gzms B secreted by the HLB-apt group were significantly higher than those of the other treatment groups and the control group." (PMID 40761795, 2025). "The results showed that compared to cGAMP, XA5508 could significantly increase the expression levels of immune factors IFN-β, IFN-γ, IL-2, IL-6, and TNFα in the mice, and significantly reduce the expression of the immunosuppressive tumor-promoting factor IL-10." (PMID 40943568, 2025). "Therefore, targeting CAFs, M2 macrophages, and TNF‐⍺ signaling alone or with other anti‐tumor drugs could represent therapeutic strategies in PM, especially for the CMS4 subtype, as indicated by this work." (PMID 39739693, 2025).
tumor (continued). "In addition, most patients with a favorable tumor histology presented low levels of IL-6 (44.4%) and TNF-α (55.6%); however, these associations were not significant p = 0.05 and p = 0.07 respectively (Table A2)." (PMID 40722593, 2025). "Therefore, reduced m6A levels in tumour‐derived EVs may promote CRC recurrence by enhancing IL‐6 and TNF‐α production by macrophages within the tumour." (PMID 40326665, 2025). "These gene-positive macrophages secreted factors such as TNF, TGFB1, and notably MIF, which is implicated in T cell suppression—suggesting a complex role of these macrophages in both propagating tumor growth as well as modulating the immune landscape to favor tumor immune escape." (PMID 40620715, 2025). "In mouse models of PDAC, parasympathetic denervation significantly increased tumor necrosis factor (TNF) levels and promoted the recruitment of tumor-associated macrophages (TAMs), thereby enhancing malignant epithelial proliferation and increasing tumor incidence." (PMID 41163091, 2025). "In addition, Michel and colleagues have demonstrated that TNFα-blockade not only reduces cardiac systolic dysfunction caused by anti-PD-1, but does not disrupt the anti-tumor efficacy of ICI." (PMID 39516409, 2025). "However, pro-inflammatory dietary components like saturated fats may counteract these benefits by activating NF-κB signaling, which upregulates angiogenic cytokines (e.g., IL-6, TNF-α) to fuel tumor progression." (PMID 40236640, 2025). "For example, IL-12 and TNF-α are associated with the promotion of the N1 phenotype, which is linked to pro-inflammatory responses, while IL-4, IL-13, and TGF-β are associated with N2 polarization, which tends to promote tissue repair, immune suppression, and tumor progression." (PMID 40486595, 2025). "However, our results suggest that, in the tumor microenvironment, the frequency of Tregs, including TNF+ Tregs, increases compared with the spleen; thus, Tregs may contribute to the pool of intratumoral TNF." (PMID 40977146, 2025). "Analysis of effector activity of these tumor-infiltrating CD4+ T cells revealed that T-bet-deficient CD4+ T cells had markedly impaired functionality in both saline and M002 treatment groups, as the IFNγ+TNFα+ population and the expression of GzmB were significantly reduced." (PMID 39885128, 2025). "Consequently, dendritic cells preferentially matured into a type 1 anti-tumor phenotype (mDC1) fostering helper T cells differentiation into Th1 cells, an anti-tumor subset of T cells, through interleukin-12 and tumor necrosis factor-alpha (TNF-α) release." (PMID 39885557, 2025). "For example, tumor-derived extracellular vesicles from human squamous head and neck cancer and lung adenocarcinoma cell lines can interact with primary monocytes and induce their activated phenotype, which is characterized by the secretion of pro-inflammatory IL-1β and TNF-α." (PMID 40427136, 2025). "Since TNF-α can exhibit both anti-tumor activities by inducing apoptosis and necrosis in tumor cells and pro-tumoral activities by regulating immune cells, we speculate that the inhibition of it by the triple treatment would suppress the pro-tumoral activity of TNF-α." (PMID 40104170, 2025). "Oral photothermal bacteria that regulate TNF-α expression could be used to mediate tumor therapy." (PMID 41181349, 2025). "Additionally, sarcopenic patients often exhibit chronic inflammatory states, such as elevated IL-6 and TNF-α levels, which may promote tumor progression and suppress immune response." (PMID 41459515, 2025). "Deepening our understanding of the molecular mechanisms underlying the HMGCR-TNF-α axis in regulating ferroptosis, in conjunction with tumor type, TNF-α signaling intensity, and HMGCR expression levels, may provide novel therapeutic targets for cancer treatment." (PMID 41450917, 2025).
tumor (continued). "Notably, miR‐146a expression is significantly elevated in NK cells from patients with HBV‐ and HCV‐related HCC, downregulating NK cell activity and reducing IFN‐γ and TNF‐α production, which renders them unable to effectively eliminate cancerous hepatocytes and promotes tumor growth and metastasis." (PMID 40060195, 2025). "Taken together, these findings indicate that targeting TNF-α or specifically the pro-tumor immunosuppressive TAMs that produce TNF-α may represent a promising therapeutic strategy to counteract the immunosuppressive microenvironment and improve treatment outcomes in PC." (PMID 40948749, 2025). "In addition, ATM inhibition could reverse the immune “cold phenotype” of tumor cells by activating the TNF-α/STAT1 signaling pathway and up-regulating the expression of MHC-I molecules." (PMID 40825766, 2025). "Indeed, TNF‐α increases the recruitment of immunosuppressive macrophage to the tumor area." (PMID 40498413, 2025). "The low levels of TNFα and IFNγ induced by both treatments might be ascribed to tumor debulking." (PMID 41471045, 2025). "The magnetotactic bacterium Magnetococcus MC-1, after surface modification, exhibited enhanced tumor accumulation under the guidance of an external magnetic field, while reducing macrophage clearance and the release of inflammatory factors such as IL-6 and TNF-α." (PMID 41155984, 2025). "Serial TNF-α measurements during treatment could inform whether a patient’s inflammatory tumor milieu is responding—for instance, a drop in TNF-α after surgery or chemotherapy might correlate with tumor reduction, whereas persistently high or rising TNF-α could signal occult disease." (PMID 40299527, 2025). "The tumor microenvironment comprises various stromal and immune cells, including cancer-associated fibroblasts, M2-polarized macrophages, regulatory T cells, endothelial cells, and mesenchymal stem cells, which secrete critical factors such as TGF-β, TNF-α, IL-6, and VEGF." (PMID 41013839, 2025). "Methylprednisolone may affect the expression of the TNF gene through the necroptosis pathway, further impacting enzymes that produce Cer and SM, ultimately leading to a decrease in Cer and SM, exerting immunosuppressive and tumor-suppressive effects." (PMID 40418396, 2025). "Moreover, the Gomisin B + cisplatin group and the YGS + cisplatin group could promote tumor tissue apoptosis and reduce the levels of inflammatory factors TNF-α, IL-1β, and IL-8." (PMID 40247422, 2025). "However, the change in TNF-α and IL-10 may mean potentially complex mechanisms of action and changes in the tumor immune microenvironment." (PMID 40575154, 2025). "Upon recognition of tumour‐associated antigens presented via MHC‐II, CD4+ T cells can differentiate into distinct effector subsets, including Th1 cells that promote cytotoxic activity through IFN‐γ and TNF‐α production, and Tfh cells that support B cell–mediated humoral immunity." (PMID 40673641, 2025). "The observed reduction in TNF levels may therefore reflect an adaptive cellular response to reduce excessive proliferation and oxidative damage, though it could inadvertently facilitate tumor progression." (PMID 41154628, 2025). "Notably, Cu/APH-M mediated the occurrence of doubly enhanced cuproptosis while triggering a powerful anti-tumor immune response (e.g., effectively promoting the upregulation and release of ICD-associated proteins and molecules, such as Caspase-1, TNF-α, CRT, HSP70, HSP90, ATP)." (PMID 40486836, 2025). "Our previous preclinical work demonstrated that combining oncolytic adenovirus encoding tumor necrosis factor alpha (TNF) and interleukin-2 (IL-2) with ICI could significantly improve tumor growth control and survival, even in ICI-resistant and refractory settings." (PMID 40465005, 2025).